BMPR1A (bone morphogenetic protein receptor type 1A)
Diseases named in the same sentence as BMPR1A in open-access papers (continued):
Sharing a sentence is not in itself a finding about the gene and the disease.
hemochromatosis (6 papers, 2012 to 2025). A disorder of iron metabolism characterized by a triad of HEMOSIDEROSIS; LIVER CIRRHOSIS; and DIABETES MELLITUS. "Furthermore, miR-122 inhibition was linked to the development of hemochromatosis by up-regulating the expression of human hemochromatosis protein (Hfe), hemojuvelin (Hjv), bone morphogenetic protein receptor type 1A (Bmpr1a) and the hepcidin antimicrobial peptide (Hamp)." (PMID 30158867, 2018). "It was proposed that miR-122 expression significantly affects mRNA transcribed by genes that control systemic iron levels, such as hemochromatosis (Hfe), hemojuvelin (Hjv), bone morphogenetic protein receptor type 1A (Bmpr1a), and Hamp." (PMID 38102707, 2023). "miR-122 inhibition increased the expression of several genes that control systemic iron levels, such as hemochromatosis (Hfe), hemojuvelin (Hjv), bone morphogenetic protein receptor type 1A (Bmpr1a) and Hamp." (PMID 22919472, 2012).
osteoporosis (6 papers, 2017 to 2025). A condition of reduced bone mass, with decreased cortical thickness and a decrease in the number and size of the trabeculae of cancellous bone (but normal chemical composition), resulting in increased fracture incidence. "In conclusion, we identified the osteoblastic BMP receptor BMPR1A as a main driver of osteoporosis in hyperthyroid mice promoting TH-induced osteoblast activity and potentially its coupling to high osteoclastic resorption." (PMID 38719881, 2024). "In conclusion, this study is the first to reveal the importance of the osteoblastic BMP receptor BMPR1A in the pathogenesis of hyperthyroidism-induced osteoporosis by coupling thyroid hormone-stimulated osteoblast activity to high bone resorption potentially via the RANKL/OPG system." (PMID 38719881, 2024). "In our study, we proposed the role of miR-204-5p-SOX11 regulation in aging osteoblasts, and the potential downstream regulation of BMPR1A/Runx2 signaling by SOX11, a signaling pathway involved in osteoporosis and OA." (PMID 29371932, 2017). "Importantly, administration of BMPR1A-Fc, a potent BMPR1A-specific BMP ligand scavenger, prevented osteoporosis in hyperthyroid mice by normalizing both bone formation and bone resorption." (PMID 38719881, 2024).
anemia (5 papers, 2018 to 2021). A reduction in the number of red blood cells, the amount of hemoglobin, and/or the volume of packed red blood cells. "Many JPS patients are asymptomatic or have nonspecific symptoms including stomachache and anemia, especially for BMPR1A-related JPS." (PMID 33327285, 2020).
gastric polyps (5 papers, 2008 to 2025). "Of those with upper GI involvement, 13(92%) had gastric polyps (five patients had the BMPR1A Bukharin mutation and four had SMAD4 mutation)." (PMID 35057835, 2022). "Indeed, we found gastric polyps in 4/7 (57%) families with the BMPR1A Bukharin mutation, and only in 6/28 (21%) other families." (PMID 35057835, 2022). "The BMPR1A variant carrier (52 years old) had only developed gastric polyps; interestingly, this same phenotype was shared by his two sisters, in whom, however, we could not perform genetic testing." (PMID 31514334, 2019). "On the other hand, by testing the BMPR1A variant carrier for germline mutations in promoter 1B of APC gene, we could exclude GAPPS, thus reinforcing the causal link between BMPR1A and gastric polyposis." (PMID 31514334, 2019). "Among two BMPR1A variant carriers with gastrointestinal polyps or cancer from FCCX-W, two hamartomatous gastric polyps at ~ 80 years of age were found in individual II.5 on histopathological scrutiny, in addition to colonic adenomas." (PMID 41023686, 2025). "Genotypic and phenotypic correlations have generally been poor with these gene mutations but a recent report has shown a strong correlation between massive gastric polyposis and the presence of a SMAD4 gene mutation versus the BMPR1A or no mutation." (PMID 18826596, 2008). "Only two participants (15%) had gastric involvement without colonic involvement (one with the BMPR1A Bukharin mutation and the other one with SMAD4), and all five participants with SB involvement had colonic involvement as well (four of them had also gastric polyps)." (PMID 35057835, 2022).
hepatocellular carcinoma (5 papers, 2023 to 2025). A malignant tumor that arises from hepatocytes. "elucidated that m6A methylation enhanced the levels of NUTM2B-AS1 by stabilizing its transcript, and the m6A-modified NUTM2B-AS1 facilitated hepatocellular carcinoma cell proliferation and stemness by epigenetically upregulating BMPR1A expression." (PMID 40641925, 2025). "Upregulation of BMP4 and BMPR1A in HCC was shown to promote proliferation and metastasis of hepatocellular carcinoma cells through activation of the MEK/ERK signaling pathway." (PMID 37443106, 2023). "The detection of BMPR1A was expected to be more sensitive and specific than the detection of PLAC8 gene methylation in patients with hepatocellular carcinoma recurrence, and PLAC8 methylation is expected to be a method that can be used to monitor the recurrence of hepatocellular carcinoma." (PMID 39766341, 2024).
hereditary mixed polyposis syndrome (5 papers, 2013 to 2024). "Patients with hereditary mixed polyposis syndrome 2 exhibit germline mutations, including frame-shift, nonsense, or missense mutations in the BMPR1A gene." (PMID 39057027, 2024).
lung carcinoma (5 papers, 2013 to 2025). "In summary, our findings demonstrated that ZEB1‐AS1 mediated bone metastasis by targeting miR‐320b/BMPR1A axis in lung cancer." (PMID 38783645, 2024). "lncRNA ZEB1‐AS1 expression was upregulated in lung cancer, which mediated bone metastasis of lung cancer through targeting miR‐320b/BMPR1A axis." (PMID 38783645, 2024). "Our study revealed that ZEB1‐AS1 mediated bone metastasis in lung cancer through targeting the miR‐320b/BMPR1A axis." (PMID 38783645, 2024). "Our findings suggested that ZEB1‐AS1 regulated cell viability, proliferation, migration, and invasion, as well as EMT, in lung cancer cells by targeting the miR‐320b/BMPR1A axis." (PMID 38783645, 2024). "Exemplifying the dichotomy of this signalling pathway in cancer, BMPR1A antagonists reduce growth and induce cell death in lung cancer cell lines." (PMID 27114889, 2016). "Moreover, our in vivo experiments confirmed that ZEB1‐AS1 mediated bone metastasis through targeting miR‐320b/BMPR1A axis in mice with lung cancer." (PMID 38783645, 2024). "ZEB1‐AS1 mediated bone metastasis through targeting miR‐320b/BMPR1A axis in lung cancer." (PMID 38783645, 2024). "Thus, we speculated that ZEB1‐AS1 may regulate bone metastasis in lung cancer by targeting miR‐320b/BMPR1A axis." (PMID 38783645, 2024). "Nevertheless, the exact function of BMPR1A in bone metastasis in lung cancer still remains unclear." (PMID 38783645, 2024). "Therefore, it is hypothesized that miR‐320b may mediate bone metastasis in lung cancer through targeting BMPR1A." (PMID 38783645, 2024). "Meanwhile, sh‐BMPR1A inhibited the regulatory effect of miR‐320b knockdown on EMT markers, proving that ZEB1‐AS1 regulated EMT process of lung cancer cells through targeting miR‐320b/BMPR1A axis." (PMID 38783645, 2024). "Our study demonstrated that the deletion of BMPR1A suppressed viability, migratory and invasive abilities, and EMT process of lung cancer cell lines, indicating the oncogenic activity of BMPR1A in bone metastasis." (PMID 38783645, 2024). "BMP7 signaling via BMPR1A and BMPR1B could inhibit the proliferation of lung cancer cells." (PMID 34036102, 2021).
myeloma (5 papers, 2015 to 2023). "Treatment with BMPR1a-Fc completely prevented myeloma-associated trabecular bone volume loss." (PMID 31586071, 2019). "In separate studies, stromal progenitors were isolated from myeloma-bearing mice following treatment with BMPR1a-Fc or control." (PMID 31586071, 2019). "In the JJN-3 model of myeloma, however, treatment with BMPR1a-Fc resulted in an increase in serum haemoglobin, concomitant with a reduction in hepatic hepcidin gene expression." (PMID 31586071, 2019). "Inhibition of BMP signalling in vivo using either a small molecule BMP receptor antagonist or a solubilized BMPR1a-FC receptor ligand trap prevents trabecular and cortical bone volume loss caused by myeloma, without increasing tumour burden." (PMID 31586071, 2019). "BMPR1a-Fc treatment was found to significantly increase trabecular bone volume and trabecular thickness in both non-tumour and myeloma-bearing mice." (PMID 31586071, 2019). "Treatment with either LDN or BMPR1a-Fc led to a significant reduction in osteoclast number and the proportion of bone surface occupied by osteoclasts in myeloma-bearing mice, with osteoclast number also reduced in non-tumour-bearing animals." (PMID 31586071, 2019). "In contrast to BMPR1a-FC, we found an activin ligand trap (ACVR2a-FC) to slightly increase osteoclastogenesis, demonstrating that BMP and activin inhibition have non-equivalent effects on myeloma bone disease in this model system." (PMID 31586071, 2019).
craniosynostosis (4 papers, 2016 to 2024). Craniosynostosis is defined as the premature fusion of one or more cranial sutures leading to secondary distortion of skull shape resulting in skull deformities with a variable presentation. "Recently, it has been reported that homozygous missense mutation of BMPR1A (results in amino acid substitution of BMPR1AR406L) develops brachycephaly with unilateral coronal craniosynostosis in humans with a slight elevation of phospho-SMAD levels." (PMID 37275223, 2023). "It should be noted that in both mice and humans, Bmpr1a/BMPR1A functions as an SuSC marker, and Bmpr1a regulates stem cell stemness, which is critical for suture patency and craniosynostosis." (PMID 39135707, 2024). "On the other hand, Bmpr1a cKO mice (Axin2Cre−Dox;Bmpr1afl/fl) develop craniosynostosis." (PMID 37275223, 2023). "In mice, constitutive activity of BMPR1A in cranial neural crest results in SMAD-dependent development of metopic craniosynostosis, and genetic deficiency for the SMAD inhibitor SMURF1 causes midline craniosynostosis." (PMID 27606499, 2016).
gastric cancer (4 papers, 2020 to 2023). A primary or metastatic malignant neoplasm involving the stomach. "7/17 JPS patients with SMAD4 variants had gastric cancer in a study by Aretz and colleagues, compared to 0/13 for BMPR1A carriers." (PMID 38066625, 2023). "Current knowledge of genotype–phenotype correlations between SMAD4 variants and JPS is that individuals are more inclined to have upper gastrointestinal (UGI) polyposis and higher gastric cancer risk, as compared to BMPR1A." (PMID 38066625, 2023). "In Blatter and colleagues’ study, 7/127 SMAD4 carriers had gastric cancer, and 0/94 in BMPR1A." (PMID 38066625, 2023).
intestinal polyp (4 papers, 2017 to 2025). Discrete abnormal tissue masses that protrude into the lumen of the intestine. "The mutations in BMPR1A and SMAD4 found in JPS suggest that the BMP pathway is implicated in the development of intestinal polyps." (PMID 36326956, 2023). "A recent finding indicated that a newly identified BMPR1A mutation (c.778+5G>C) in JPS could influence mRNA splicing, suggesting that irregularities in alternative splicing might significantly contribute to the formation of intestinal polyps in JPS." (PMID 40226309, 2025).
rectal cancer (4 papers, 2014 to 2024). A primary or metastatic malignant neoplasm that affects the rectum. "RUNX3 was significantly associated with rectal cancer survival, while BMP1 (PARTP = 0.099) and BMPR1A (PARTP = 0.085) were marginally significant." (PMID 25541970, 2014).
adenoma (3 papers, 2013 to 2025). A neoplasm arising from the epithelium. "The small intestine was affected with carcinoma(s) or adenomas in five BMPR1A variant carriers, all from HNPCC20 (III.1, III.6, IV.10, IV.13, and IV.20)." (PMID 41023686, 2025). "Apart from LOH, we addressed somatic BMPR1A point mutations, too, as possible inactivating “second hits” in adenomas and carcinomas from our BMPR1A-associated families." (PMID 41023686, 2025). "However, BMPR1A expression was significantly lower in gallbladder adenocarcinoma than in peritumoral tissues, adenomas, polyps and chronic cholecystitis tissues." (PMID 23531103, 2013). "BDNF was significantly higher (positive) and BMPR1A was significantly lower (negative) in gallbladder adenocarcinoma than in peritumoral tissues, adenoma, polyps, and chronic cholecystitis (P < 0.01 for both)." (PMID 23531103, 2013).
atherosclerosis (3 papers, 2015 to 2022). A disease characterized by the build-up of fatty material and calcium deposition in the arterial wall resulting in partial or complete occlusion of the arterial lumen. "This is of interest because BMPR1A has been implicated in vascular calcification as well as in the development of atherosclerosis, and platelets play a role in pathogenesis of the latter." (PMID 26024889, 2015). "Amongst these differentially expressed genes, we noted a positive association between BMPR1A-biased BMP2 expression and GPR176, an orphan G-protein coupled receptor thought to be involved in atherosclerosis." (PMID 27114889, 2016).
colitis (3 papers, 2021 to 2023). Inflammation of the colon. "The perturbation of epithelial Bmpr1a has been shown to amplify BMP4 levels in the context of dextran sodium sulphate (DSS)-inuced colitis." (PMID 37628872, 2023). "It was found that the reduced expression of BMP4 and BMPR1A was co-related with colon injury and inflammation in DSS-induced colitis, and the colonic inflammation and damage could be enhanced through deletion of BMPR1A." (PMID 34692671, 2021).
diabetes (3 papers, 2015 to 2019). "This study also reports that individuals with impaired glucose tolerance or overt diabetes show increased expression levels of BMPR1A in WAT." (PMID 27209464, 2016). "Reduction of BMPR1A signaling mediated by Cre recombinase under the control of the rat insulin promoter (RIP) was shown to induce diabetes from 2–3 months of age." (PMID 26187948, 2015). "As Pdx1-dnBmpr1a and insulin promoter-derived Bmpr1a-deleted mice develop diabetes at 2–3 months of age, we also performed intraperitoneal glucose challenge in our pBmpr1aKO mice at 3 months of age." (PMID 26187948, 2015). "Involvement of BMPs in glucose metabolism has also been demonstrated in mice with attenuated BMPR1A signaling in β-cells, which lead to decreased expression of key genes involved in insulin gene expression, glucose sensing and diabetes due to impaired insulin secretion." (PMID 30539233, 2019).
hereditary hemorrhagic telangiectasia (3 papers, 2020 to 2025). A disorder of angiogenesis leading to arteriovenous dilatations: cutaneo-mucosal hemorrhagic telangiectasias and visceral shunting. "JPS patients with SMAD4 mutations predominantly exhibit upper gastrointestinal polyps and hereditary hemorrhagic telangiectasia (HHT), while BMPR1A-mutated patients mainly present with colonic phenotypes." (PMID 40226309, 2025).
holoprosencephaly (3 papers, 2008 to 2023). Holoprosencephaly (HPE) is a complex brain malformation resulting from incomplete cleavage of the prosencephalon, occurring between the 18th and 28th day of gestation, and affecting both the forebrain and face, which results in neurological manifestations and facial anomalies of variable severity. "Genetic studies performed on mouse models showed that double knockout of Bmpr1A and Bmpr1B leads to the development of holoprosencephaly." (PMID 37284286, 2023). "Genetic analysis based on the double mutant of Bmpr1A and Bmpr1B showed the existence of two kinds of holoprosencephaly." (PMID 37284286, 2023). "However, the requirement of BMP signaling for dorsal telencephalic development is shown after forebrain-specific ablation of Bmpr1A or the double knock-out of Bmpr1A and Bmpr1B, which leads to holoprosencephaly." (PMID 23761735, 2013).
osteoarthritis (3 papers, 2004 to 2017). A noninflammatory degenerative joint disease occurring chiefly in older persons, characterized by degeneration of the articular cartilage, hypertrophy of bone at the margins and changes in the synovial membrane. "However, the control mice used in this study were heterozygous for a null allele of Bmpr1a, and they showed little sign of osteoarthritis even late in life." (PMID 15492776, 2004). "In human arthritis, the BMP ligands 2 and 6 and their receptors BMPR1a and BMPR2 were upregulated, while BMP ligands 4 and 5 were downregulated in RA and osteoarthritis (OA) synovium in comparison to normal control samples." (PMID 25889670, 2015).
ovarian carcinoma (3 papers, 2010 to 2023). A malignant neoplasm originating from the surface ovarian epithelium.
pulmonary fibrosis (3 papers, 2022 to 2025). Chronic progressive interstitial lung disorder characterized by the replacement of the lung tissue by connective tissue, leading to progressive dyspnea, respiratory failure, or right heart failure. "Downregulation of BMPR1A and upregulation of miR-503-5p in BLM treated WT mice may suggest a possible underlying mechanism of pulmonary fibrosis." (PMID 35083615, 2022). "But the role of BMPR1A in BLM-induced pulmonary fibrosis is currently unknown." (PMID 35083615, 2022).
squamous cell carcinoma (3 papers, 2013 to 2020). A carcinoma arising from squamous epithelial cells. "However, it should be noted that contradictory findings were found for squamous cell carcinoma of the lower lip, where strong expression of BMPR1A showed a significant association with advanced clinical staging and high malignancy score." (PMID 23531103, 2013). "Our previous work in mammary gland BMPR1a knockout studies resulted in a unique shift to alternate focal morphologies in the knockout tumors, exhibiting more desmoplastic, carcinoma-like or squamous cell carcinoma-like features." (PMID 32318332, 2020).
Arthritis (2 papers, 2004 to 2015). Inflammation of a joint. "The development of severe arthritis symptoms in Bmpr1a-deficient mice raises the possibility that defects in BMP signaling also contribute to human joint disease." (PMID 15492776, 2004). "The three major limb phenotypes revealed by eliminating Bmpr1a with Gdf5-driven Cre include webbing between digits, lack of joint formation at specific locations in the ankle, and failure to maintain articular cartilage after birth, resulting in severe arthritis." (PMID 15492776, 2004).
atrial septal defect (2 papers, 2019 to 2022). Interauricular communication is a congenital malformation characterized by a communication between the atrial chambers of the heart. "We report on a patient with a homozygous missense variant in BMPR1A causing skeletal abnormalities, growth failure a large atrial septal defect, severe subglottic stenosis, laryngomalacia, facial dysmorphisms, and developmental delays." (PMID 31493347, 2019).